MIR6724-1 (microRNA 6724-1)
Synonyms: MIR6724; hsa-mir-6724; hsa-mir-6724-1
Gene: MicroRNA gene on chromosome 21 (8,205,315 to 8,205,406, forward strand). Ensembl gene ENSG00000275950.
Homologues: Paralogues in human: MIR6724-2 (100% identical), MIR6724-3 (100% identical), MIR6724-4 (100% identical).